MYC (MYC proto-oncogene, bHLH transcription factor)
Diseases named in the same sentence as MYC in open-access papers (continued):
Sharing a sentence is not in itself a finding about the gene and the disease.
hepatoblastoma (36 papers, 2011 to 2026). Hepatoblastoma (HB) is a malignant hepatic tumor and is the most common pediatric liver cancer. "Altogether, these observations provide ample biological rationale why panobinostat is working so efficiently in MYC/NPM1-associated hepatoblastoma cells." (PMID 39529166, 2024). "Here we generate a hepatocyte-specific MYC-driven multifocal hepatoblastoma-like tumor model that resembles high-risk human hepatoblastoma." (PMID 37414763, 2023). "Here, we report an improved MYC-driven hepatoblastoma-like murine model that recapitulates the pathological features of embryonal type of hepatoblastoma, with transcriptomics resembling the high-risk gene signatures of the human disease." (PMID 37414763, 2023). "HUH6 and HepG2 cells exhibited stronger transcriptomic activation of AFP, DUSP9, GPC3, DLK1, MYC compared to other non‐hepatoblastoma cell lines." (PMID 40271711, 2025). "Our recently developed mouse model of MYC-driven hepatoblastoma showed that tumors express high levels of Igf2 (ranked #1 among the differentially expressed genes), supporting the notion that IGF2 plays an important role in tumorigenesis." (PMID 40684183, 2025). "Integrated studies define MYC inhibition by panobinostat as a novel treatment element to be introduced into the therapeutic strategy for patients with metastatic hepatoblastoma." (PMID 39529166, 2024). "We provide evidence that panobinostat inhibits tumor growth and induces apoptosis of hepatoblastoma cells by robustly downregulating MYC at the protein level." (PMID 39529166, 2024). "We furthermore described NPM1 as a surrogate marker for MYC activation in hepatoblastoma, which we found to be predominantly expressed in metastatic hepatoblastoma, but also in many other cancers." (PMID 39529166, 2024). "Other molecular abnormalities contributing to hepatoblastoma development include overexpression of MYC and IGF2, as well as various epigenetic modifications, such as abnormal DNA methylation patterns and histone modifications." (PMID 39596558, 2024). "Comparing the embryonal to the fetal components of hepatoblastoma, upregulated pathways included Wnt signaling, MYC targets, E2F targets, mitotic spindle, G2M checkpoint, and DNA repair genes." (PMID 39567523, 2024). "Strikingly, the response of MYC-expressing hepatoblastoma cells to panobinostat was 10-times stronger than the one of Kras-driven tumor cells, whereas the antitumor effect of cisplatin and doxorubicin were comparable in both models." (PMID 39529166, 2024). "Altogether, these results clearly indicate that panobinostat selectively impacts MYC-expressing hepatoblastoma." (PMID 39529166, 2024). "Here the authors report and characterize a hepatocyte-specific, MYC-driven hepatoblastoma mouse model and show it recapitulates the human hepatoblastoma pathophysiology." (PMID 37414763, 2023). "CD326, MYC, and CK19 expression have previously been associated with a poor prognosis for hepatoblastoma and is more often found on tumors described as embryonic in origin." (PMID 36845728, 2023). "Novel data suggest that deregulation of c-MYC function is not only associated with HCC development, but also with CLD (e.g., ALD, viral hepatitis, liver fibrosis/cirrhosis, for hepatoblastoma and cholangiocarcinoma, etc.)." (PMID 35008356, 2021). "Some pathways related to hepatoblastoma molecular mechanisms were detected, including the well-studied Wnt/β-catenin and MYC pathways." (PMID 34367972, 2021). "To study the effect of let-7 on carcinogenesis, we employed an inducible MYC-driven hepatoblastoma model." (PMID 26445246, 2015). "Here, we confirmed the tumor suppressor activity of an endogenous transgenic let-7 in a MYC-driven hepatoblastoma model." (PMID 26445246, 2015). "Similarly, in our MYC-driven mouse model of hepatoblastoma, we identified a population of tumor cells with high expression of erythroid genes." (PMID 40684183, 2025).
hepatoblastoma (continued). "We therefore generated a protein–protein interaction network to identify a putative surrogate marker that could substitute MYC in being indicative for MYC activation in hepatoblastoma." (PMID 39529166, 2024). "Thus, MYC deactivation displays a promising therapeutic strategy in hepatoblastoma, as for many hematological and solid malignancies as well, but so far, MYC has been considered “undruggable” in the clinical setting." (PMID 39529166, 2024). "which is consistent with the known role for MYC in sustaining hepatoblastoma growth." (PMID 37414763, 2023). "A study showed that LIN28B is sufficient to drive liver tumors in the let-7 miRNA dependent and independent ways in endogenous tumor models and is over-activated in mouse models of MYC-driven hepatoblastoma 19, which indicates its essential role in the development of hepatoblastoma." (PMID 32284747, 2020). "Only sixteen of the thirty mouse tumors analyzed for DNA copy number alterations yielded RNA suitable for genome-wide analysis, so we added an additional four mouse hepatoblastomas that were generated by hydrodynamic tail-vein injection of an inducible MYC expression plasmid." (PMID 25738607, 2015). "These tumors resemble hepatoblastoma based on their early onset, their characteristic histology and the expression of specific markers such as GPC3 and EPCAM, but most importantly high MYC expression." (PMID 39529166, 2024). "Although the functions of CDK7 in hepatoblastoma have yet to be explored, CDK7 inhibition disrupts the transcriptional dependency of MYC-driven cancer." (PMID 37414763, 2023). "Nevertheless, we only observed well differentiated hepatoblastoma in P67 while embryonal and cholangioblastic subtypes occur at an early time (P7, P25), suggesting that there could be a sequential event during MYC-mediated cellular transformation that coopts with liver developmental program." (PMID 37414763, 2023). "We first performed a transcriptomic evaluation of the two well‐recognized hepatoblastoma cell lines, HepG2 and HUH6, using Pearson's analysis with gene signatures in the public GSE168997 dataset to elucidate IGF2′′s role in hepatoblastoma (AFP, DUSP9, GPC3, DLK1, MYC, EPCAM, KRT8, and LIN28B)." (PMID 40271711, 2025). "Pathway enrichment analysis of the essential genes using the ‘Genetic and Chemical Perturbation database’51 showed that they are enriched in class 2 hepatoblastoma genes (CAIRO_HEPATOBLASTOMA_CLASSES_UP, n = 612), and are targets of BMP2, DREAM complex, MYC and β-catenin." (PMID 37414763, 2023). "Though MYC is not necessary for hepatoblastoma development, depletion of MYC delays tumor progression through reducing fatty acid transporter CD36 expression, with a concomitant decrease in LDs accumulation and FAO levels." (PMID 29907133, 2018). "We previously found that the deletion of Lin28a and Lin28b impaired the growth of MYC-induced pediatric hepatoblastomas in vivo, but the absence of Lin28a/Lin28b did not completely eliminate their initiation, possibly due to the high levels of MYC overexpression in that model." (PMID 38875287, 2024). "One of the 2 subclasses of hepatoblastoma on gene expression profiling is allied with greater genetic instability (gains of chromosomes 8q and 2p), overexpression of hepatic progenitor cell markers (AFP, Cytokeratin 19, and EpCAM), and upregulated MYC signaling." (PMID 37600579, 2023).
myeloid leukemia (36 papers, 2008 to 2026). A clonal proliferation of myeloid cells and their precursors in the bone marrow, peripheral blood, and spleen. "The importance of MYC function in cancer was discovered in the late 1970s when the sequence of the avian retrovirus that causes myelocytic leukemia was identified." (PMID 35582389, 2021). "Transcriptome analysis of both patient samples and K562 myeloid leukemia cells overexpressing RUNX1::ERG revealed consistent MYC repression by the fusion protein." (PMID 37002311, 2023). "MYC upregulation is usually moderate in myeloid leukemias, yet, enough to generate radical changes in the myeloid precursor differentiation." (PMID 32110991, 2020). "Many genetic aberrations have prognostic impact on myeloid leukemias, including the overexpression of the MYC, CIP2A, and SET oncogenes." (PMID 32110991, 2020). "It has recently been identified as a component of the SWI/SNF chromatin-remodeling complex, bound to the BRG1 ATPase subunit, and able to support the proliferation of myeloid leukemia cells via sustained MYC transcription." (PMID 31652979, 2019). "Another PIM2/MYC mouse (mouse #8) showed myeloid leukemia phenotype as judged by FACS analysis, and we were able to establish an in vitro cell line of myeloid phenotype (Gr-1+, Mac-1+, B220-)." (PMID 26606454, 2015). "MYC, as one of the key transcription factors in hematopoiesis, is frequently overexpressed in human acute lymphoblastic and myeloid leukemia." (PMID 26517351, 2015). "We show that aggressive myeloid leukemia develops when any of the PIM kinases are expressed in mouse bone marrow in conjunction with MYC." (PMID 25238262, 2014). "Transplantation of murine bone marrow co-expressing MYC and PIM1, PIM2 or PIM3 caused rapid and uniformly lethal myeloid leukemia." (PMID 25238262, 2014). "PIM kinases co-expressed with MYC have produced an aggressive myeloid leukemia in mice and silencing this family will increase chances of leukemic cells to initiate apoptosis." (PMID 25238262, 2014). "Our MYC-driven mouse model shows that all three PIM members behave similarly in driving tumorigenesis by accelerating MYC-induced myeloid leukemia." (PMID 25238262, 2014). "Our in vivo model reveals that all PIM kinase family members can cooperate with MYC to induce myeloid leukemia." (PMID 25238262, 2014). "In a murine model, similar to other anti-apoptotic proteins, BCL2A1 expression has recently been shown to accelerate the onset of myeloid leukemia induced by MYC over-expression." (PMID 23118966, 2012). "Retroviral expression of MYC in bone marrow cells like here seems more often to result in predominance of myeloid leukemia, possibly due to lower levels of MYC than in the Vav promoter system." (PMID 22393362, 2012). "Moreover, we found previously that MSI2 binds and regulates c-MYC translation in myeloid leukemia cells." (PMID 36167829, 2022). "There have been many in vitro- and in vivo- based studies on the role of MYC in myeloid leukemias." (PMID 34372899, 2021). "Increased MYC can accelerate the development of myeloid leukemia in APL." (PMID 26545364, 2015). "All PIM family members, in combination with MYC, rapidly and lethally accelerated myeloid leukemia." (PMID 25238262, 2014). "In mice all three PIM kinases, co-expressed with MYC, drastically accelerated myeloid leukemia." (PMID 25238262, 2014). "It is likely that an early expansion of the MYC-transformed myeloid leukemia cells is counteracted by MYC-induced apoptosis that is overcome by BCL-XL or BCL-2 expression, resulting in an almost immediate tumor transformation of myeloid CD11b/Gr1-positive cells, subsequently causing AML." (PMID 22393362, 2012). "It has been established that MYC alone induces a myeloid leukemia, and the co-expression of high levels of all anti-apoptotic proteins in their model simply accelerated the time to presentation of the myeloid leukemia phenotype." (PMID 23118966, 2012).
myeloid leukemia (continued). "Most reports where MYC is expressed broadly in hematopoietic cell types in mice, it seems to generate either myeloid leukemia, T lymphoma or a mix of these two tumor types like here, which may reflect different levels of MYC depending on expression systems used." (PMID 22393362, 2012). "Deregulation of the MYC oncogene, along with the inactivation of PP2A, is persistently found in myeloid leukemias, inducing tumor progression and conferring poor prognosis." (PMID 32110991, 2020). "In this review, we focus on the role of MYC and PP2A in the myeloid leukemia initiation and progression." (PMID 32110991, 2020). "In myeloid leukemia cell lines, we found binding of MYC at the FBXO11 promoter but did not observe peaks in undifferentiated embryonic stem cell or lymphoblast lines." (PMID 41542766, 2026). "Additionally, m6A has been shown to enhance the translation of c-MYC, BCL2, and PTEN mRNAs in human myeloid leukemia MOLM13 cells." (PMID 40453361, 2024). "Several early studies on myeloid leukemia cell lines, such as MEL, K562, and U937, showed that MYC up-regulation could inhibit cell differentiation." (PMID 34372899, 2021). "Here, we focus on and discuss the role of MYC and PP2A in myeloid leukemias." (PMID 32110991, 2020). "Even though the levels of MYC after PP2A activation have not been clearly defined in myeloid leukemias, it is known that the levels of PP2A activity indirectly correlate with the ones of MYC." (PMID 32110991, 2020).
renal carcinoma (36 papers, 2011 to 2025). A carcinoma arising from the epithelium of the renal parenchyma or the renal pelvis. "HIFs can also directly induce MYC gene expression in the case of a single nucleotide polymorphism in the MYC promoter associated with risk for renal cancer." (PMID 33803184, 2021). "Though this analysis itself cannot implicate any specific polymorphism in the regulation of MYC in renal cancer, it is consistent with the data above implicating an rs35252396-associated phenotype." (PMID 27774982, 2016). "In line with the results from RNA analyses, positive MYC protein staining was strongly associated with the clear cell phenotype in a tissue microarray containing 453 unselected renal cancer specimens (Erlangen RCC Cohort)." (PMID 27774982, 2016). "Notably, increased levels of MYC protein and MYC-target genes are linked to worst prognosis in renal carcinoma." (PMID 27366943, 2016). "PRMT7 regulates the expression of the proto-oncogene c-MYC and has been shown to promote renal cancer cell growth and accelerate tumor development in a c-MYC dependent manner." (PMID 38911125, 2024). "These hub proteins are important for the development of renal cancer, and MYC was the most common hub, being upregulated in both categories." (PMID 37047552, 2023). "HIF-1α inhibits c-MYC activity, whereas HIF-2α has been shown to promote c-MYC-dependent proliferation in renal carcinoma cells and multiple other cell lines." (PMID 30857245, 2019). "Previous reports have established a relationship between HIF-2α and MYC-induced transcription in renal carcinomas, with MYC regulation of metabolism functioning in concert with and independent of HIF-1 signaling." (PMID 31675502, 2019). "HIF binding, activity and accessibility of the enhancer as well as MYC/PVT1 induction are restricted to cells from renal tubular origin and dependent on the genotype of rs35252396, a polymorphism associated with renal cancer susceptibility." (PMID 27774982, 2016). "We demonstrate here that unrestrained activation of HIF in pVHL-defective renal cancer enhances expression of MYC and PVT1 via long distance interactions with a HIF-binding intergenic enhancer." (PMID 27774982, 2016). "That many of the currently known renal cancer-associated SNPs (EPAS1, CCND1 and MYC/PVT1) can be linked to modulation of a single pathway (that is, the HIF pathway) is striking and to our knowledge unique in tumour biology." (PMID 27774982, 2016). "Also, downregulation of respiration in renal carcinoma cells has been attributed to the action of the HIF pathway on the activity of MYC and PGC1α, which regulate mitochondrial biogenesis." (PMID 34021238, 2021). "Our data suggest that MYC and VEGF are negatively regulated by RASSF10 and that combination of high RASSF10 and low MYC or VEGF expression is associated with a favorable prognosis for renal cancer patients." (PMID 32047266, 2020). "Thus, our data suggest that PVT1 may act as an oncogene in renal carcinoma via stabilization of MYC protein, and subsequently activation of MYC pathway." (PMID 27366943, 2016). "In renal carcinoma cell lines, PLX decreased cell viability only at relatively high IC50 concentrations, between 7–10 μM, and also decreased c-MYC expression dose-dependently." (PMID 33803654, 2021). "As a first step in analysing mechanisms associated with variant rs35252396, we therefore sought to define the frequency of dysregulated MYC and PVT1 expression in renal cancer." (PMID 27774982, 2016). "Strikingly, significant induction of both MYC and PVT1 RNA by DMOG was specifically observed in renal cancer cell lines and tubular cells." (PMID 27774982, 2016). "However, in colon and renal cancer cells, FOXO1 acts downstream of the PI3K/AKT signalling pathway, promoting the downregulation of MYC expression and inhibiting PD‐L1 expression." (PMID 38899748, 2024).
renal carcinoma (continued). "Especially, the expression of c-MYC, KLF4, OCT4, NANOG and SOX2 implies that these 5 factors are involved in carcinogenesis and progression of RCC, and probably there are RCC cancer stem cells existing in renal carcinoma." (PMID 21982273, 2011). "This revealed robust HIF-binding signals across a series of pVHL-defective renal cancer cell lines as well as immortalized proximal tubular and primary tubular cells in which HIF was stabilized by hypoxia or DMOG at intergenic sites located between the MYC and PVT1 genes." (PMID 27774982, 2016).
cholangiocarcinoma (35 papers, 2013 to 2024). A carcinoma that arises from the intrahepatic biliary tree (intrahepatic cholangiocarcinoma) or from the junction, or adjacent to the junction, of the right and left hepatic ducts (hilar cholangiocarcinoma). "In vitro assays showed that Dhea and 2–14,15-Eg inhibited cholangiocarcinoma cellular viability, proliferation, and migration inhibiting expression of MYC." (PMID 35113866, 2022). "This study suggested that Dhea and 2–14,15-Eg were novel potential inhibitors of MYC targeting, as well as are a promising drug in dealing with cholangiocarcinoma and have a perspective application." (PMID 35113866, 2022). "c-MYC;AKT-expressing hepatocytes formed cholangiocarcinoma (CCA), as revealed by the glandular morphology of the tumors and by the expression of the cholangiocyte marker Osteopontin (OPN)." (PMID 39195268, 2024). "To identify novel targets for the diagnosis, treatment and prognosis of cholangiocarcinoma, we screen ideal lead compounds and preclinical drug candidates with MYC inhibitory effect from the ZINC database, and verify the therapeutic effect of Dhea and 2–14,15-Eg on cholangiocarcinoma." (PMID 35113866, 2022). "As a result, MYC and CCND1 are upregulated leading to CRC progression and angiogenesis.Circ-CCAC1 derived from extracellular vesicles disrupts endothelial barrier integrity when translocated onto endothelial monolayers thereby inducing angiogenesis in cholangiocarcinoma (CCA)." (PMID 37819576, 2023).